SOX2 (SRY-box transcription factor 2)
Diseases named in the same sentence as SOX2 in open-access papers (continued):
Sharing a sentence is not in itself a finding about the gene and the disease.
cancer (continued). "Furthermore, transcription factors such as Nanog, OCT4, SOX2, and KLF4, which are critical for maintaining stem cell pluripotency, have been found to interact with EMT regulators to enhance the stem-like characteristics of cancer cells." (PMID 39403386, 2024). "So, the next question would be why SOX2 does not play a role in certain cancer types." (PMID 38334608, 2024). "Since cancer stem cells (CSCs) have the ability to self-renew and are less sensitive to therapy which makes them often responsible for resistance occurrence, we checked the gene expression levels of stemness-related transcription factors, OCT4, NANOG, and SOX2." (PMID 37239024, 2023). "The self-renewal characteristic of cancer cells can be attributed to the phenotypes of stem cells, characterized by increased expression levels of stemness transcription factors such as OCT4 (octamer-binding transcription factor 4), NANOG (Nanog homeobox), and SOX2 (sex-determining region Y-box 2)." (PMID 38132948, 2023). "The Yamanaka factors, consisting of SOX2, KLF4, OCT4, and MYC, have been pivotal in mediating the induction of pluripotent stem cells from terminally differentiated fibroblasts—an epochal achievement in stem cell research that has reverberated into the study of cancer stem cells." (PMID 38132318, 2023). "In addition, mesenchymal stem cells of the bone marrow may play a critical role in the de-differentiation of cancer cells that reach the bone marrow and their transformation to CSCs by inducing stem cell markers like CD133, OCT4 and SOX2." (PMID 37834336, 2023). "Moreover, adipocyte-co-cultured cancer cells displayed an increased expression level of stem cell markers (CD44, OCT4, and SOX2) which could also be further promoted via CD36 overexpression." (PMID 37371076, 2023). "Here, we report that the antifungal agent ciclopirox olamine (CPX), a potential candidate for drug repurposing in cancer treatment, is able to reprogram gastric non-CSCs into cancer stem-like cells via activation of SOX2 expression and increased expression of C-MYC, HIF-1α, KLF4, and HMGA1." (PMID 37686684, 2023). "Also, OCT4, Sox2, Nanog, CD44 and CD133 are generally known as cancer stem-like cell markers." (PMID 36632615, 2023). "Notably, SOX2, OCT4, KLF4, and the pluripotency reprogramming facilitator c-MYC, known for their role in establishing and maintaining stem cell pluripotency, are also aberrantly expressed in certain cancer cells." (PMID 37760529, 2023). "In addition, the protein and mRNA expression levels of USP6NL, pluripotency and cancer stem cell markers (CD44 and CD133), transcription factor (Nanog and SOX2), and efflux transporter ABCG2 were significantly overexpressed in the U87MG-R and T98G-R sphere compared with the parental control." (PMID 35884836, 2022). "In most of these cancers, SOX2 expression is correlated with negative outcomes." (PMID 35454854, 2022). "Interestingly, SNAI1-KO cells presented higher stem cell frequency and underwent a switch in the expression of cancer stemness signaling genes, with significant upregulation of epithelial KIT, ALDH1A1 and SOX2, and analogous downregulation of mesenchymal CD44 and SOX9." (PMID 36171192, 2022). "One mechanism that could explain this lower HNSCC incidence is the downregulation of cancer stemness and epithelial–mesenchymal transition-related genes, such as OCT4, SOX2 and NANOG, observed after metformin treatment, which could inhibit progression in cancer-initiating cells." (PMID 35327549, 2022). "Furthermore, AGXT may upregulate the stemness transcription factors SOX2 and OCT4 to maintain cancer stemness in LCSCs." (PMID 35625596, 2022). "Hybrid EMT cells will express epithelial transcription factors such as TP63 or SOX2, and mesenchymal ones, such as SNAIL/SLUG, ZEB1/2 or TWIST1/2, in a way where the expression of genes required for migration or growth can switch on demand depending on the cancer cell’s needs." (PMID 35159370, 2022).
cancer (continued). "Additionally, we evaluated the expression of some cancer‐related proteins in ex vivo tumors from both groups, including proliferation (Ki‐67 and Cyclin D1), anti‐apoptotic (BCL2), and stemness (NESTIN and SOX2) markers, collected at distinct time points according to animal survival times." (PMID 34919784, 2022). "Along with the positive immunofluorescence for cancer stem cell biomarkers (OCT4, NANOG, and SOX-2), these findings indicated the involvement of primitive embryonic cells as the origin of MCMT and concluded that MCMT may not come from colliding tumors, but from a single stem cell." (PMID 36187098, 2022). "In addition, knockdown of CMTM2 could antagonize the effects of SJZ on SGC7901 cells' expression of SOX2, NANOG, and CD44 and their cancer stem cell-like properties." (PMID 35873650, 2022). "Finally, with the Wnt/β-catenin pathway being involved in GBM stem-like maintenance and considering the close link between GBM resistance and cancer stem cell presence, we wanted to analyze the effect of the COX-2 inhibitor alone or in combination with TMZ on the SOX-2 expression in T98G cells." (PMID 35163465, 2022). "SATB2 may be a driving force for developing cancer stem‐like phenotypes in damaged hepatocytes where induction of stem cell markers (CD44, CD90, EpCAM, AFP and LGR5) and pluripotency maintaining factors (POU5F1/Oct4, Sox‐2, Nanog and KLF4) was prominent." (PMID 35152538, 2022). "Furthermore, the biological effects of AGXT-induced SOX2 and OCT4 between parental live cancer cells and LCSCs may be different." (PMID 35625596, 2022). "Of interest, overexpression of KMO has been suggested to contribute to the malignant phenotype of TNBC cells, particularly cancer stem cell (CSC) properties, and 3) KMO-induced β-catenin stabilization, which also leads to increased expression of pluripotent genes such as Nanog, Oct4, and Sox2." (PMID 36077608, 2022). "In addition, the downregulation of SPN also induces an increase in the stemness properties of the cells, such as the expression of some cancer stem cell markers (NANOG, OCT4, SOX2, and KLF4) and enrichment in CD44+/CD24- cells, cancer-initiating cells in breast tumors with stem cell properties." (PMID 34066428, 2021). "Additionally, SOX2 and NANOG are expressed in both the nucleus and cytoplasm in many cancer cells." (PMID 33572108, 2021). "Of note, we also found that some of the published SOX2 primers we tested were actually amplifying non-specific transcripts and we had to test several before choosing the ones that worked logically for human embryonic stem cells and cancer cells." (PMID 33471801, 2021). "Additionally, protein destabilization of other stemness factors, such as SOX-2 or OCT-4, by mimicking their AKT-dependent phosphorylation domains, may also be a practical approach to improve cancer treatment efficacy and warrants further investigation." (PMID 34163000, 2021). "The enrichment of cancer cells with pluripotency features after treatments with 4OHT and fulvestrant in PDS cultures as depicted by gene expression analysis, was further supported by an increase in Sox2 protein levels, and a reduction in PgR and Ccna2 proteins levels." (PMID 34172801, 2021). "Thus, the aberrant expression of Sox2 is a necessary but not sufficient condition for this protein to confer cancer stemness." (PMID 34287231, 2021). "Because the introduction of SOX2, OCT4, MYC, and KLF4 is sufficient to reprogram differentiated cells into iPSC with ESC properties, the combined expression of these factors has been hypothesized to initiate tumors and promote cancer progression." (PMID 32427884, 2020).
cancer (continued). "The ability of the tested compounds to downregulate the metabolic genes through HDAC11 and Sox2 might be a feature that will enable these inhibitors to eliminate stem-like and non-stem-like cancer cells simultaneously." (PMID 32170113, 2020). "While manipulation of CAMK2A expression in cancer cells induced corresponding functional changes consistent with its TIC supportive role including self-renewal, xenograft tumorigenecity at low cell doses, and resistance to targeted or cytotoxic therapy, silencing SOX2 abrogated these effects." (PMID 32483123, 2020). "LSD1 blockade with the small molecule inhibitor CBB1007 has been shown to enhance repressive H3K9 methylation at the stemness-specific enhancer of SOX2, thereby validating the notion that LSD1 might serve as a selective epigenetic target for therapeutic ablation of SOX2-driven cancer stemness." (PMID 32191225, 2020). "Also, the fluorescence signals of Sox2 (green) and Oct4 (red) were highly overlapped with nucleus (DAPI in blue), where both stemness regulators triggered the transformation process from ordinary cancer cells to CSCs." (PMID 32764400, 2020). "The cancer stem cells in medullary thyroid carcinoma are characterized by chemo- and radio-resistance induced by increased signaling pathways, such as signal transducer and activator of transcription 3 (STAT3), c-Met, SOX2, rearranged during transfection (RET), CD44." (PMID 32244473, 2020). "While Sox2 might not be directly involved in the survival of differentiated cancer cells, its downstream targets like HK2 and PDK2 might be contributing in viability of the cells through their key roles in metabolic processes." (PMID 32170113, 2020). "Cell sorting based on CD44 and CD24 expression or ALDH (aldehyde dehydrogenase) activity revealed that most Sox2 high expresser cells were not CD44hi/CD24lo- or ALDH-positive cells suggesting that they were not CSCs (cancer stem cells), though CD44 played a role in Sox2 expression." (PMID 33228022, 2020). "g., transfection) of stemness genes, such as OCT3, SOX2, KLF4, MYC, NOTCH1, NANOG, and LIN28, as well as epithelial-mesenchymal transition (EMT) genes (ZEB1, SNAI, VIM, TWIST, etc.), leads to stem phenotype induction and increased stem-like cancer cell activity." (PMID 32523653, 2020). "Sox2 is a β-catenin transcriptional target, upregulated in cancer stem cells, and absent in normal epidermis, while Ptgs 2, or better known as Cox2, is a pro-inflammatory gene that induces prostaglandins production from arachidonic acid resulting in cytokine upregulation and inflammatory reactions." (PMID 33080912, 2020). "Finally, EGFR inhibitors, Gefitinib and Erlotinib, and Src inhibitor, Dasatinib, are all shown to reduce the levels of SOX2 by blocking the EGFR/SRC/AKT signaling, eventually suppressing the self-renewal properties of cancer stem cells in non-small cell lung cancer." (PMID 31748974, 2020). "Furthermore, aberrant STAT3 expression may play a role in maintaining survival and plasticity of cancer stem cells, as STAT3 is known to support pluripotency by upregulating sox2 [SRY-box 2], Nanog [Homeobox protein nanog], and c-myc [MYC proto-onco gene]." (PMID 31105556, 2019). "It is worth to emphasise that the majority of GB cells are SOX2-positive, as it is in contrary to the assumptions that cancer stem cells constitute only so-called side population or, it is possible that SOX2 is a marker not characteristic solely for stem cells." (PMID 32089685, 2019). "Deregulated expression of miRNA-140-5p, well-known for the critical role in cancer development, was detected in preoperative breast cancer patients at various stages and regulates BCSC expression by modulating various signaling pathways such as Wnt, SOX2, and SOX9." (PMID 31530793, 2019).
cancer (continued). "Furthermore, to explore the functions of TGIF1 in regulating cancer stem cell (CSC) properties, we compared the expression levels of stemness transcriptional factors, such as Sox2, Nanog, CD44, Nestin, and CD133, between the TGIF1-deficient PDAC cells and TGIF1-sufficient PDAC cells." (PMID 31109321, 2019). "Patients with SCLC without neurological symptoms were similar in age, percentage female and SCLC disease extent at cancer diagnosis to those SCLC patients with neurological presentations whether they had SOX2 antibodies or not." (PMID 30445363, 2019). "Moreover, we observed a positive association of SOX2 with EGFR expression in stage IV metastatic endometrial carcinoma, but not in early stage cancer." (PMID 30510261, 2018). "Furthermore, cancer stem cell markers, such as CD133, SOX2, OCT4 and NANOG were down-regulated." (PMID 28415621, 2017). "In addition, Sox2, PAK4 and c-Myc are regulators of cancer cell proliferation." (PMID 29137251, 2017). "Consequently, if SOX2 acts as a transcriptional repressor of HPV16-LCR, its down-regulation in cancer cells could eventually promote an increase in the LCR activity, reflected as an overexpression of the E6 and E7 oncogenes." (PMID 28678184, 2017). "In addition, SOX2 functions with VEGF and drives cancer-initiating stem cells." (PMID 28335793, 2017). "However, the mechanisms by which SOX2 and other CSC markers are overexpressed in cancer are unknown." (PMID 28460458, 2017). "In this study, we analysed eleven death-from-cancer signatures in survival of cancer patients and demonstrated that USP22 plays vital roles in gastric CSC self-renewal and GC progression by stabilizing BMI1 and regulating the expression of stemness genes such as CD133, SOX2, OCT4 and NANOG." (PMID 28415621, 2017). "However, on transfection of the mammospheres with SOX2 siRNA, the IC50 reduced to 3 nM, indicating that reduced SOX2 expression could increase chemosensitivity of the stem cell compartment of cancer cells." (PMID 28835684, 2017). "However, such analyses are often based on a limited number of cancer cell lines, thus the proposed SOX2 targets are not regulated by SOX2 in other cell lines that are not included in the analyses." (PMID 26846300, 2016). "SOX2, a member of the SRY-related HMG-box (SOX) family of transcription factors, stimulates the reprogramming of adult cells into induced pluripotent stem cells and maintains stem cell-like properties in cancer by complexing with other stem cell markers such as NANOG and OCT4." (PMID 26706028, 2015). "Furthermore, normal and cancer stem cells share phenotypes that may reflect the activity of common signalling pathways, such as high expression of NANOG, OCT4 and SOX2, which is reduced by oestrogen." (PMID 24178749, 2014). "The importance of stem cell markers in identifying cancer stem cells, including Frizzled-4, Lgr5, and CD133 have previously been demonstrated, and here our data suggest that their expressions may be dependent on common precursor protein Sox2." (PMID 25380620, 2014). "However, it appears that Sox2 expression in cancer does not always correlate with increased invasiveness and metastasis." (PMID 23815808, 2013). "Although the oncogenic potential of stem cell factors, such as Sox2, has been hypothesized to be based on the “stemness” similarity between stem cells and cancer cells, Sox2’s function in cancer cells is not clearly understood." (PMID 23451179, 2013). "The cdODN-SOC tested in this study is potentially applicable to a wide spectrum of cancers, as the target transcription factors/pluripotency maintaining factors Sox2, Oct4 and c-Myc are not cell/tissue specific; they are overexpressed in SP cells of various origins." (PMID 24040121, 2013). "Thus, ectopic expression of Sox2 does not appear to confer properties characteristic of cancer stem cells." (PMID 23326489, 2013).
cancer (continued). "However, higher levels of Oct4 expression were significantly associated with poorer differentiation and higher TNM stage of the cancer (p < 0.05), whereas Sox2 did not have this correlation." (PMID 22837720, 2012). "Notably, embryonic transcription factors, including SRY-box transcription factor 2 (SOX2), octamer-binding transcription factor 4 (OCT4), and Nanog homeobox (NANOG), are vital for preserving the self-renewal capacity and undifferentiated state of CSCs in various cancers." (PMID 41522355, 2026). "Given that cancer progression involves the loss of differentiation and acquisition of stem cell-like features, we examined the effect of TC2N expression on three stem cell markers (SOX2, OCT4, and NANOG) in normal lung (without urethane treatment) and urethane-induced lung tumor tissues." (PMID 39849581, 2025). "However, there have been no reports on the significance of K75 acetylation of Sox2 in cancers." (PMID 38473392, 2024). "Additionally, the proto‐oncogene MYCN was upregulated together with SOX2 and YAP1, both markers for stem cell self‐renewal, reprogramming and homeostasis, as well as mechanistically promoting proliferation, survival, invasion/metastasis, cancer stemness and drug resistance." (PMID 36819185, 2023). "Interestingly, it has also been demonstrated that SOX2 overexpression induces fibronectin 1 (FN1) through the PI3K/AKT/NF-kB pathway in cancer; therefore, it is not excluded that this occurrence could be valid also for BC." (PMID 37238229, 2023). "Therefore, GBM cancer cells could shift cancer cells from the proliferation state to hibernation state through autophagy as a survival function, followed by enhancement of CD133/CD44/Nestin/SOX2 as GSC markers to support the stochastic model." (PMID 34069945, 2021). "During the formation of iCSCs from non-stem cancer cells exposed to radiotherapy, these signaling events have been shown to coincide with other complementary pathways, including pluripotency maintenance reprogramming (SOX-2, OCT4, NANOG) and plasticity, and to configure iCSCs." (PMID 31867574, 2019). "This event could either be followed by further deregulations in stem cell-genes, such as Sox2, which result in the development of aggressive cancer stem cells, or if no further deregulations of stem cell-genes occur then a state of cell differentiation-like is encouraged instead." (PMID 28736504, 2017). "However, this does not mean that SOX2 levels cannot rise during cancer." (PMID 28388544, 2017). "However, for most cancers, the link between SOX2 and their TIC has not been firmly established." (PMID 28388544, 2017). "To further investigate whether cancer cells cultured in a 3D matrigel microenvironment acquire stem cell–like characteristics when compared with 2D monolayer cells, we measured the expressions of the stem cell markers OCT4, SOX2, NANOG, c-MYC and LIN28 in both 2D- and 3D-cultured A549 cells." (PMID 25883172, 2015). "Moreover, we demonstrated that loss of BMI-1 in EC cells reduces expression of stemness gene SOX-2, KLF4 and drug-resistance gene MRP-1, suggesting that BMI-1 expression maybe required for the proliferation of cancer cells, as well as for regulation of stemness properties of EC cells." (PMID 21851624, 2011). "CSC transcription factors (such as SOX2, OCT4, KLF4 and CD44) are important marker of cancer and normal stem cells." (PMID 39611488, 2025). "RT-PCR analysis showed significantly (p<0.01) higher expression of prominent stem cell factors—SOX2, OCT4, and NANOG—in CD133+EpCAM+ cells compared to their negative fractions, corroborating their characterization as cancer stem-like cells." (PMID 40677705, 2025). "Although there were few differences in gene expression in surviving cancer cells after Pembrolizumab treatment, PDS cultures not-responding to the treatment had significantly higher SOX2 and lower MKI67 expression compared to responding PDS cultures." (PMID 40240529, 2025).